SPAG11B (sperm associated antigen 11B)
Description:
Has antimicrobial activity against E.coli (By similarity). Plays a role in the defense response in the male reproductive tract, contributing to sperm maturation, storage and protection (By similarity).
Synonyms: He2; EP2; EP2C; EP2D; EDDM2B; HE2C; SPAG11
Tractability: Antibody: UniProt places it where antibodies can reach, with high confidence; UniProt predicts a signal peptide or a membrane-spanning region; its Gene Ontology location is reachable by antibodies, with medium confidence.
Gene: Protein-coding gene on chromosome 8 (7,442,684 to 7,463,674, reverse strand). Ensembl gene ENSG00000164871.
Subcellular location: Secreted
Subcellular location (Human Protein Atlas): Golgi apparatus; Predicted to be secreted
Gene Ontology:
Biological process: spermatogenesis
Cellular component: extracellular region
Genetic constraint (gnomAD): Loss-of-function variants: 5 observed, 6.08 expected, observed/expected ratio (o/e) 0.82, 90% interval 0.43 to 1.64. That is too few expected variants to judge how well the gene tolerates losing a copy. Missense variants: 38 observed, 78.46 expected, observed/expected ratio (o/e) 0.48, 90% interval 0.37 to 0.63. Synonymous variants: 12 observed, 27.27 expected, observed/expected ratio (o/e) 0.44, 90% interval 0.28 to 0.71.
Homologues: Orthologues: chimpanzee SPAG11B (59% identical), macaque SPAG11B (48% identical), mouse Spag11b (37% identical), dog SPAG11B (35% identical). Paralogues in human: SPAG11A (98% identical).
Diseases named in the same sentence as SPAG11B in open-access papers:
SPAG11B is named in the same sentence as 6 diseases in open-access papers, as found by Europe PMC text mining. Sharing a sentence is not in itself a finding about the gene and the disease. The quoted sentences say what the papers report.
Arthritis (1 paper, 2017). Inflammation of a joint. "Likewise, in transduced animals, both GFP and SPAG11B/C were still detected 14 days after mice knee joint transduction, indicating a stable expression of transgenes, even after the induction of arthritis, wherein an extensive hyperplasia of fibroblast-like synoviocytes occurred." (PMID 28587618, 2017). "Indeed, this hypothesis was supported by our results, wherein Mcpt-6 gene expression as well as tryptase-like activity were upregulated 7 days after mBSA/IL-1β-induced arthritis to levels seemingly not counterbalanced by endogenous tryptase inhibitors, such as SPAG11B/C." (PMID 28587618, 2017).
male infertility (1 paper, 2025). The inability of the male to effect fertilization of an ovum after a specified period of unprotected intercourse. "A causal link was observed between male infertility and Lactococcus (OR = 1.05, 95% CI = 1.00–1.11, P = .048) and between SPAG11B and Coprococcus 2 (β = 0.08, 95% CI = 0.01–0.14, P = .02) but not with other gut microbiota genera." (PMID 40295237, 2025).
SPAG11B also shares sentences with these, for which no sentence is quoted: bacterial infections (1 paper); infectious disease (1); otitis media (1); psoriasis (1).